SLIT3 (slit guidance ligand 3)
Diseases named in the same sentence as SLIT3 in open-access papers (continued):
Sharing a sentence is not in itself a finding about the gene and the disease.
Anxiety (3 papers, 2018 to 2020). Intense feelings of nervousness, tension, or panic often arise in response to interpersonal stresses. "Taken together, loss of Slit3 may result in disrupted neural circuits related to motor function and increased anxiety-like states, which are co-occurring symptoms in ASD." (PMID 30483073, 2018). "Anxiety-like behaviors in Slit3-KO mice were further assessed by measuring the duration that animals spent in the open arm of the elevated plus maze." (PMID 30483073, 2018). "For example, female Slit3-KO mice displayed anxiety-like behaviors in the elevated plus maze test and open field test while male KO mice did not." (PMID 30483073, 2018). "The increased anxiety-like state in Slit3-KO mice was further supported by anxiety-like behaviors observed in the elevated plus maze test and the light/dark box test." (PMID 30483073, 2018). "In order to assess anxiety-like behaviors in Slit3-KO mice, explorative behavior in the center of the arena during the first 10 min of the open field test was analyzed." (PMID 30483073, 2018). "The observed anxiety-like behaviors in Slit3-KO mice were further assessed based on the number of transitions that animals made between light and dark compartments." (PMID 30483073, 2018). "As these brain areas are known to be involved in the regulation of anxiety, the observed expression pattern implicates that Slit3 may be critical to the development and regulation of neuronal circuits for anxiety." (PMID 30483073, 2018). "The Slit3-KO mice spent reduced percentage of time in the open arm of the maze compared to WT mice (U = 338, p = 0.007, Mann–Whitney test), indicating heightened anxiety-like states in the KO mice." (PMID 30483073, 2018). "It is possible that the presence of SLIT3 in the hippocampus may be involved in anxiety regulation but not memory, as previous studies show that the dorsal and ventral hippocampus regulate memory and anxiety respectively." (PMID 30483073, 2018). "In summary, Slit3-KO mice showed aberrant motor behaviors and anxiety-like behaviors, suggesting that Slit3 may play an important role in neural circuits for motor function and anxiety regulation." (PMID 30483073, 2018). "Behavioral assessments in Slit3-KO mice revealed that the absence of Slit3 resulted in increased anxiety-like behaviors and altered motor behaviors." (PMID 30483073, 2018).
Parkinson disease (3 papers, 2018 to 2022). A progressive degenerative disorder of the central nervous system characterized by loss of dopamine producing neurons in the substantia nigra and the presence of Lewy bodies in the substantia nigra and locus coeruleus. "A disease association of SNPs in the SLIT3 gene and genetic risk (models: susceptibility, survival and age-at-onset) for Parkinson disease was previously identified in two independent GWAS datasets." (PMID 31404076, 2019). "In addition, the association of single nucleotide polymorphism of SLIT3 with Parkinson's disease, a disorder mainly focused on motor functions, further supports the importance of SLIT3 for the maintenance of motor pathways." (PMID 30483073, 2018).
postmenopausal osteoporosis (3 papers, 2020 to 2023). Metabolic disorder associated with fractures of the femoral neck, vertebrae, and distal forearm. "In this context, systemic treatment with recombinant SLIT3, which promotes type H endothelium growth, ameliorates bone loss in experimental models of fracture healing and postmenopausal osteoporosis." (PMID 37601109, 2023). "Xu et al17 showed enhanced bone fracture healing and counteracted bone loss in a mouse model of postmenopausal osteoporosis by administration of recombinant SLIT3." (PMID 33448495, 2020).
schizophrenia (3 papers, 2005 to 2022). A major psychotic disorder characterized by abnormalities in the perception or expression of reality. "SLIT3 was reported to increase schizophrenia susceptibility." (PMID 35912095, 2022).
autism (2 papers, 2018 to 2021). Persistent deficits in social interaction and communication and interaction as well as a markedly restricted repertoire of activity and interest as well as repetitive patterns of behavior. "The precise mechanism through which SLIT3 mutations contribute to autism symptoms needs further investigation." (PMID 30483073, 2018). "Importantly, SLIT3 is suggested as an autism-risk gene by several genetic studies." (PMID 30483073, 2018). "Additionally, the prevalence of autism is different in sex and our previous study in animal models also showed the sex difference in behaviors of Slit3-KO mice." (PMID 33504340, 2021). "Since behavioral criteria are relevant to the diagnosis of ASD, Slit3-KO mice with behavioral characterization may be a useful animal model for the study of clinical interventions in autism." (PMID 30483073, 2018). "Thus, deletion of SLIT3 may result in aberrant development/maintenance of motor functions and lead to impaired motor coordination or reduced locomotive behaviors in autism." (PMID 30483073, 2018). "Yet the causal link between SLIT3 mutation and autism symptoms has not been examined." (PMID 30483073, 2018).
breast tumors (2 papers, 2004 to 2016). "We have now demonstrated that SLIT3 5′ CpG island similar to SLIT2 is frequently hypermethylated in colorectal and glioma tumours and less so in breast tumours." (PMID 15534609, 2004).
cutaneous melanoma (2 papers, 2016 to 2022). A primary melanoma arising from atypical melanocytes in the skin. "Down-regulation of ROBO1 is part of a molecular signature that predicts the metastatic risk associated with cutaneous melanoma, therefore we examined the survival of patients with SLIT3 mutations." (PMID 27095580, 2016).
diaphragmatic hernia (2 papers, 2018 to 2020). A congenital or acquired weakness or opening in the diaphragm which allows abdominal contents to protrude into the chest cavity; congenital diaphragmatic hernias are caused when the embryonic diaphragm fails to fuse. "Despite its neuronal expression, the most prominent phenotype seen in Slit3 deficient mice is postnatal diaphragmatic hernia with no obvious neuronal or axon pathfinding defects having been reported." (PMID 32209227, 2020). "However, congenital diaphragmatic hernias have been identified in absence of Slit3,20,90 indicating that Slit3 is important for the division of the coelomic cavities." (PMID 29538649, 2018).
fibrosis (2 papers, 2018 to 2024). the formation of excess fibrous connective tissue in an organ or tissue in a reparative or reactive process. "Our accumulated data suggest that SLIT3 significantly regulates Ang II-induced cardiac fibrosis and fibroblast differentiation via the RhoA/ROCK1 signaling pathway." (PMID 38800023, 2024). "In addition, SLIT3 could regulate cardiac fibrosis by controlling the TGF-β/Smad signaling pathway and the fibrotic gene expressions." (PMID 38800023, 2024).
Insulin resistance (2 papers, 2022 to 2025). Increased resistance towards insulin, that is, diminished effectiveness of insulin in reducing blood glucose levels. "These genes have been involved in insulin resistance and secretion (ATM, PTPRN2, PSMD10, and NSF), adipogenesis (SLC25A24 and PAX8), inflammatory processes (TNFRSF8 and SLIT3), and mitochondrial processes (PM20D1 and LCLAT1)." (PMID 36535927, 2022).
neuroblastoma (2 papers, 2011 to 2025). Neuroblastoma (NB) is the most common solid, extracranial childhood tumor. "Future studies are needed to clarify the specific profile of PKC isoforms and the microenvironmental conditions through which hypoxia regulates neuroblastoma differentiation and how these interact with SLIT3-mediated pathways." (PMID 40448172, 2025). "Stage 4S-specific tumor cell subpopulation exhibits a spontaneous regression-like program, from which SLIT3 mediates intratumoral crosstalk and promotes neuroblastoma differentiation via PLCβ/PKC signaling." (PMID 40448172, 2025). "Collectively, these results demonstrated the capacity of SLIT3 to induce neuroblastoma cell differentiation in vitro." (PMID 40448172, 2025). "Collectively, our data suggested that PLCβ/PKC signaling plays an essential role in mediating SLIT3-induced neuroblastoma cell differentiation." (PMID 40448172, 2025). "To further investigate the effects of SLIT3 on neuroblastoma cells, we first treated neuroblastoma cell lines with SLIT3 recombinant protein and monitored changes in cell morphology." (PMID 40448172, 2025). "Further experimental investigation demonstrated that SLIT3 conveys intratumoral crosstalk leading to neuroblastoma differentiation in vitro and in vivo." (PMID 40448172, 2025). "Overlapping PKC isoforms likely serve as the molecular foundation shared between hypoxia-induced and SLIT3-induced neuroblastoma differentiation, suggesting the potential of hypoxia to regulate SLIT3-induced differentiation." (PMID 40448172, 2025). "Mechanistically, PLCβ/PKC signaling mediates SLIT3-induced neuroblastoma cell differentiation." (PMID 40448172, 2025). "To investigate whether PLCβ and its downstream PKC signaling pathway mediate SLIT3-induced neuroblastoma differentiation, we employed the PLCβ inhibitor U-73122 and PKC inhibitor Ro 31–8220 for signaling inhibition." (PMID 40448172, 2025). "Mechanistically, PLCβ/PKC signaling mediates the SLIT3-induced neuroblastoma cell differentiation." (PMID 40448172, 2025). "In addition, hypoxia has been reported to play a role in regulating neuroblastoma differentiation, and Hypoxia-Inducible Factor 1-alpha (HIF1α) is capable of binding to the SLIT3 promoter." (PMID 40448172, 2025). "Meanwhile, three independent neuroblastoma cohorts (Kocak, SEQC, TARGET) consistently revealed significantly elevated expression of NRCAM, VSTM2L, SLIT3, and ALCAM in Stage 4S tumors." (PMID 40448172, 2025). "However, the roles and downstream mechanisms of SLIT3 and SLIT-ROBO signaling in the context of neuroblastoma remain largely unexplored." (PMID 40448172, 2025).
osteoarthritis (2 papers, 2025 to 2026). A noninflammatory degenerative joint disease occurring chiefly in older persons, characterized by degeneration of the articular cartilage, hypertrophy of bone at the margins and changes in the synovial membrane. "More importantly, Slit3 knockdown/knockout in osteoclasts results in reduced sensory nerve innervation in the osteochondral regions, decreased osteoarthritis pain, and alleviated bone and cartilage degeneration in TMJ-OA." (PMID 41255240, 2025). "This study tests the hypothesis that osteoclast-derived slit guidance ligand 3 (SLIT3) plays an important role in osteoarthritis pain." (PMID 41255240, 2025).
Osteopenia (2 papers, 2020 to 2023). Osteopenia is a term to define bone density that is not normal but also not as low as osteoporosis. "Mice that knockdown Slit3 or its receptor Robo1 exhibit an osteopenia phenotype as a result of increased bone resorption and reduced bone formation." (PMID 36636821, 2023).
renal agenesis (2 papers, 2013 to 2023). Renal agenesis (RA) is a form of renal tract malformation characterized by the complete absence of development of one or both kidneys (unilateral RA or bilateral RA respectively), accompanied by absent ureter(s). "Mice that are homozygous for this Slit3 allele have renal agenesis and CDH and usually die at birth or shortly thereafter." (PMID 23536828, 2013). "Further studies will be needed to determine the molecular mechanism by which decreased SLIT3 expression causes renal agenesis in Slit3-null mice and modulates the prevalence of renal agenesis caused by FREM1 deficiency." (PMID 23536828, 2013). "Slit3-null mice also have unilateral and bilateral renal agenesis that is similar to that seen in FREM1-deficient mice." (PMID 23536828, 2013). "Phenotypic similarities–CDH and renal agenesis–also exist between FREM1-deficient mice and mice with recessive mutations in Slit3, which encodes an extracellular matrix protein." (PMID 23536828, 2013). "This suggests that Frem1 and Slit3 interact genetically in the development of renal agenesis and that Slit3 expression can modulate the penetrance of this FREM1-related phenotype in mice." (PMID 23536828, 2013). "These experiments reveal that Frem1 interacts genetically with Gata4 in the development of lung lobulation defects and with Slit3 in the development of renal agenesis." (PMID 23536828, 2013). "We found that Frem1 and Gata4 interact genetically in the development of lung lobulation defects and that Frem1 and Slit3 interact genetically in the development of renal agenesis." (PMID 23536828, 2013). "This increase was more that could be attributed to the additive effect of the disrupted Slit3 allele, since renal agenesis was not seen in Frem1eyes2/+;Slit3+/− mice (0/126)." (PMID 23536828, 2013). "Mice that lack the extracellular matrix protein SLIT3 develop a central form of CDH and have a high rate of renal agenesis." (PMID 23536828, 2013). "CDH, renal agenesis and lung lobulation defects were not seen in any of the Frem1eyes2/+ or Frem1eyes2/+;Slit3+/− mice with the exception of one Frem1eyes2/+ mouse in which lung lobulation defects were identified." (PMID 23536828, 2013). "Renal agenesis was not seen in Frem1eyes2/+ mice (0/110) or in Frem1eyes2/+;Slit3+/− mice (0/126)." (PMID 23536828, 2013).
aortic regurgitation (1 paper, 2023). "In regards to BAV adult patients with variants in ROBO1, ROBO2, SLIT1 and SLIT3 genes, the presence of BAV-related complications such as aortic regurgitation, aortic stenosis, and AscAA was checked." (PMID 36855159, 2023).
arteriovenous malformations (1 paper, 2025). "Research has indicated that SLIT3 mutations or dysregulation may be associated with arteriovenous malformations (AVMs), particularly in the brain." (PMID 40564170, 2025).
autism spectrum disorder (1 paper, 2019). A spectrum of developmental disorders that includes autism, and Asperger syndrome. "Notably, OXT, Robo2 and Slit3 have all been implicated in Autism spectrum disorders." (PMID 31180321, 2019).
colon cancer (1 paper, 2022). "As a novel type of tumor suppressor gene, SLIT3 has been reported to play a role in breast, liver, lung, and colon cancer, and the promoter methylation of SLIT3 has been reported to be involved in tumor occurrence and progression." (PMID 35953532, 2022).
essential tremor (1 paper, 2022). A relatively common disorder characterized by a fairly specific pattern of tremors which are most prominent in the upper extremities and neck, inducing titubations of the head. "SLIT3 may also play a role in essential tremor disease pathogenesis." (PMID 35396452, 2022).
gastric tumor (1 paper, 2025). "During early gastric tumor progression, methylation of CpG islands inactivates SLIT1, SLIT2 and SLIT3." (PMID 40508075, 2025).
gastroschisis (1 paper, 2022). Gastroschisis is marked by viscera protruding, without a covering sac, from the fetal abdomen on the right lateral base of the umbilicus. "A group of researchers reported on a mutant mouse with gastroschisis that had a mutation in Slit3, as well as an extra point mutation in Fam171A1, a related family member that has 35% amino acid identity with FAM171B." (PMID 36248192, 2022).
Iron deficiency (1 paper, 2019). "Iron deficiency altered methylation at the genes regulating ephrin B signaling/ephrin receptor signaling (data not shown), including increased methylation at Ephb1, Itsn1, Prkar1b, and Srgap2, and decreased methylation at Arhgef15, Mknk1, and Slit3 loci." (PMID 31137889, 2019).
liver diseases (1 paper, 2018). "Subsequently, we hypothesized that Slit3 regulated HCC tumor growth through manipulation of the GSK3β/β-catenin pathway which is commonly associated with the development of HCC and other liver diseases." (PMID 29859044, 2018).
lung squamous cell carcinoma (1 paper, 2017). "Additionally, we also compared the levels of miR-218, SLIT2 and SLIT3 in lung squamous cell carcinoma subtype and normal tissues." (PMID 28830450, 2017).
nicotine dependence (1 paper, 2020). Physical and psychological dependence on nicotine. "Associations between detailed nicotine dependence phenotypes and SLIT3 genotype in a Finnish twin cohort (n = 1715)." (PMID 32209227, 2020).
osteopetrosis (1 paper, 2021). Osteopetrosis, also known as marble bone disease, is a descriptive term that refers to a group of rare, heritable disorders of the skeleton characterized by increased bone density on radiographs. "At seven loci, there was a single putative causal gene: Abca12 at a locus for adult neurogenesis; Epha4 (stress-coping strategy); Pkn2, Slit3, and Pgk1-rs7 (at three different loci for sleep); H60c (home cage activity); and Adcy1 (osteopetrosis)." (PMID 34311762, 2021).
osteosarcoma (1 paper, 2016). A usually aggressive malignant bone-forming mesenchymal neoplasm, predominantly affecting adolescents and young adults. "Transposon insertions were found in Srgap2, Enah, Slit2, Slit3, or Robo1 in 24 percent of primary tumors from mice with Sleeping Beauty derived osteosarcoma, further implicating the role of the Slit-Robo pathway in osteosarcoma." (PMID 27966608, 2016).
pancreatic cancer (1 paper, 2022). "This included elements of the Hedgehog signaling pathway (SHH, GAS1), semaphorin signaling (SEMA3A, PLXNA1, PLXNB2, PLXND1, PLXNA2, FARP1, FARP2) and also axon guidance pathways (ROBO1, SLIT1, SLIT3 and SLITRK2), all notable for their involvement in pancreatic cancer progression and metastasis." (PMID 36429078, 2022).
peripheral nerve injury (1 paper, 2019). Injury to a peripheral nerve. "Previous studies on Slit focusing on SCs suggested that peripheral nerve injury could lead to the expression of various neurotrophic factors in SCs, including NGF, BDNF, neurotrophin 4/5, insulin growth factor 1 and 2, and Slit2 and Slit3." (PMID 31607866, 2019).
septal defects (1 paper, 2019). "This is the first study to find an association of SLIT2 and SLIT3 with predisposition to human CHD, although, of note, a recent study identified ROBO1 loss-of-function SNVs in cases with TOF and septal defects." (PMID 31613678, 2019).
spinal muscular atrophy (1 paper, 2017). A motor neuron disease that affect the muscles, and characterized by muscle weakness and atrophy resulting from progressive degeneration and irreversible loss of the anterior horn cells in the spinal cord (i.e., lower motor neurons) and the brain stem nuclei. "Recently, Ottesen and his colleagues shown that SLIT3 is one of most strongly upregulated genes in the a spinal muscular atrophy model, which presented disturbed testis development, degenerated seminiferous tubules, decreased sperm count and low fertility." (PMID 28553232, 2017).
squamous cell carcinoma (1 paper, 2022). A carcinoma arising from squamous epithelial cells. "Hypermethylation of three CpGs (cg13261825, cg03260566 and cg01663016) in SLIT1, SLIT2 and SLIT3 genes was found at a higher prevalence in adenocarcinoma than in squamous cell carcinoma, although the difference was not statistically significant." (PMID 35053460, 2022).
temporal lobe epilepsy (1 paper, 2019). A localization-related (focal) form of epilepsy characterized by recurrent seizures that arise from foci within the temporal lobe, most commonly from its mesial aspect. "SLIT3 maps to temporal lobe epilepsy in DISGENET (C0014556) but a disease association with SLIT3 has not been described in OMIM." (PMID 31404076, 2019).